CCL2 (C-C motif chemokine ligand 2)
Diseases named in the same sentence as CCL2 in open-access papers (continued):
Sharing a sentence is not in itself a finding about the gene and the disease.
cancer (continued). "CCL2 provided recruitment of immune cells under carcinomas conditions and inflammatory responses." (PMID 34249913, 2021). "Recent studies showed that CCL2 also regulates cancer metastasis." (PMID 32986377, 2020). "In lung cancer, CCL2 is linked to Docetaxel resistance through PI3K/Akt pathway activation, inhibiting caspase 3-dependent apoptosis; this review is focused in platinum drugs, but chemokines also affect other cancer drugs such as Docetaxel or Tamoxifen." (PMID 32499779, 2020). "Besides cancer cells, also cancer-associated fibroblasts (CAFs), characterized by the expression of fibroblast activation protein (FAP-)α, release high amount of CCL2, leading to sustain MDSC infiltration in pMNs." (PMID 32133298, 2020). "The CCL2 protein was moderately expressed in normal tissues and lowly expressed in cancer tissues." (PMID 32649310, 2020). "Potential effect of IL-4 and IL-13 (250 ng/mL, 24 h) on the expression of genes encoding proteins relevant for cancer development by facilitating angiogenesis (HIF1A and VEGFA), inflammation (PTGS2, NOS2, CCL2), and metabolic reprogramming (GLUT1, ODC1, NOS2) was evaluated." (PMID 32512917, 2020). "Furthermore, CCL2 is produced in all types of cancers and plays a particularly important role in cancer metastasis." (PMID 33224886, 2020). "In addition, increased CCL2 production by splenic myeloid cells and stromal cells in cancer appears to contribute to the accumulation of myeloid progenitors, which upregulate their CCR2 expression in the spleen." (PMID 33042791, 2020). "expression by TAMs with the release of CCL2 by the cancer cells." (PMID 33028808, 2020). "Since TAMs can secrete CCL2, which in turn recruit more macrophages at the tumor site, it may play an indispensable role in the modulation of angiogenesis and cancer progression." (PMID 32992449, 2020). "Interestingly, we did not observe a relationship between the proteasome ChT-L activity and serum CCL2 concentration, which is another potential factor responsible for cancer progression." (PMID 32886667, 2020). "Cancer cells acquire a migratory and invasive phenotype that invades adjacent tissues by disrupting the extracellular matrix and migrates toward the blood and lymphatic vessels in an early stage of CCL2-induced metastasis." (PMID 33297571, 2020). "During this stage, CCL2 guides the migration of cancer cells through linking with CCR2." (PMID 32850861, 2020). "CCL2 promotes cancer cell intravasation and extravasation because it is a chemoattractant for TAMs." (PMID 32850861, 2020). "Inhibition of CCL2/CCR2 has been explored in the clinical setting as a possible cancer therapeutic." (PMID 33247183, 2020). "Similarly, the undifferentiated MPRO cells expressed higher levels of Il-1β, Ccl2, Ccl3, Ccl4, and iNos when cultured in the supernatant of cancer cells compared to SF media." (PMID 33049964, 2020). "For example, evidence from our studies indicated that co-culturing of TNBC cells with mesenchymal stromal cells (MSCs) or cancer-associated fibroblasts (CAFs) in the presence of TNFα or IL-1β stimulation has given rise to contact-dependent increase in CXCL8, CCL2 and CCL5 levels in the co-cultures." (PMID 32605277, 2020). "CCL2 from adipocytes promotes cancer progression by increasing angiogenesis." (PMID 32674405, 2020). "Because of the multifunctional nature of CCL2, the blockade of the CCL2–CCR2 axis may cause unexpected effects on cancer patients." (PMID 33297571, 2020). "Important chemokines frequently targeted in inflammation and cancer are CCL2, IL-8 and CXCL12." (PMID 32244723, 2020). "Nitro-CCL2 recruits monocyte derived suppressor cells and repels trafficking of cytotoxic T cells and Th1 effector cells, confining T cells in stromal regions that surround cancers cells." (PMID 33262763, 2020). "Moreover, experimental studies using xenotransplanted tumors have revealed the involvement of the CCL2/CCR2 axis in cancer metastasis." (PMID 33330033, 2020).
cancer (continued). "However, at this stage CCL2 can also recruit neutrophils, which have a destructive effect on cancer cells." (PMID 33182504, 2020). "C-C Motif Chemokine Ligand 2 (CCL2, also known as monocyte chemotactic protein 1), was demonstrated to be involved in the progression of several cancers by activating PI3K/Akt, Rac GTPase and p42/44 MAPK signaling pathway and by recruiting different subsets of myeloid cells." (PMID 33066172, 2020). "CCL2 is known to be highly abundant in the cancer microenvironment." (PMID 32655574, 2020). "In addition, CCL2 promotes the migration of cancer cells by inducing the expression of MMP2 as well as MMP9." (PMID 32850861, 2020). "In most cancer models, blocking the CCL2/CCR2 axis leads to a strong decrease in TAM abundance." (PMID 31417566, 2019). "Interestingly, FBXW7 expressed in the host microenvironment also suppressed cancer metastasis depending on the FBXW7/NOTCH/CCL2 axis." (PMID 30341246, 2019). "In addition, carlumab (CNTO88), an anti-CCL2 monoclonal antibody, has been shown to prevent the development of several cancers in mouse models." (PMID 31629410, 2019). "Moreover, when co-cultivated with cancer cells, CAFs produced a higher level of CCL-2, which stimulate CSCs by inducing Notch-1 expression and thereby activating the Notch signaling pathway." (PMID 31417869, 2019). "In addition to IL6, monocyte chemoattractant protein 1 (MCP-1/CCL2) has been linked to intestinal tumorigenesis and to cachexia in human cancer patients." (PMID 31731747, 2019). "Another factor that may account for the alterations of myeloid cell populations is decreased expression of Ccl2 by LLC-sh21 cancer cells recovered from tumors." (PMID 31133614, 2019). "Furthermore, we revealed that the crosstalk between infiltrating macrophages and cancer cells promoted the CCL2 production by cancer cells, which in turn, led to sustained myeloid cell-mediated inflammation in residual tumors." (PMID 31780645, 2019). "Accordingly, CCL2 secretion by breast tumor cells activated Wnt-1 production by mammary intra-epithelial macrophages inducing an epithelial/mesenchymal transition-like signaling on cancer cells and driving early cancer dissemination." (PMID 31417566, 2019). "These contrasting effects call for a more detailed investigation in single cancer types, as they might be accountable for the failures in therapeutically targeting CCL2 (see Discussion and Conclusions)." (PMID 31921102, 2019). "After recruitment, TAMs can also produce CCL2, suggesting that a positive feedback loop may exist in the crosstalk between cancer cells and TAMs." (PMID 31781676, 2019). "However, the mechanisms through which CCL2/CCR2 signaling promotes cancer progression are poorly understood." (PMID 31208996, 2019). "For instance, the CCL-2 neutralizing antibody has been shown to significantly suppress tumorigenesis and inhibit pro-stemness Notch signaling in an orthotopic breast cancer model involving the co-implantation of cancer cells and CAFs." (PMID 31417869, 2019). "Notably, CCL2 together with its cognate receptor CCR2 have shown to play important roles in cancer cell survival." (PMID 31207928, 2019). "Based on our data we hypothesize that HER2+ early cancer cells attract macrophages locally and in response to the CCL2 signal these macrophages also produce CCL2, as macrophages from WT mammary glands expressed lower levels of CCL2." (PMID 29295986, 2018). "These genes included CCL2, which is known to attract MDSCs in cancer microenvironment." (PMID 29168083, 2018). "The mechanism by which CCL2 impacts on cancer is reported to be widely diverse." (PMID 30059519, 2018). "CCL2 is highly expressed and secreted from cancer cells and contributes to cancer progression." (PMID 30237493, 2018). "However, again, in comparison to HEK, the expression of CCL2 in the cancer cell lines UD-SCC 8, UD-SCC 2, UD-SCC 1 and HeLa was significantly upregulated for most of the concentrations tested." (PMID 30266096, 2018).
cancer (continued). "Interestingly, we observed significant increase of CCL2 serum levels in cancer patients based on stage of disease compared with entire control group." (PMID 30151375, 2018). "In addition, both inflammatory chemokine CCL2 and inflammatory factor TNFα have been identified as crucial promoters of cancer progression and metastasis." (PMID 29650964, 2018). "The production of CCL2 led to the MDSC accumulation in cancer environment." (PMID 29168083, 2018). "Moreover, CCL2 regulates cancer stem cells through an abnormal Notch activation in various tissues, which is also fundamental to BC." (PMID 30059519, 2018). "Most recently, this concept has been shown to be important in neutrophil-based anticancer activity, where apoptotic cancer cells release epigenetically regulated cytokines such as CXCL1, CXCL10, and CCL2, driving nucleic acid-elicited phagocytosis of dying cancer cells by neutrophils." (PMID 29666625, 2018). "Therefore, this mouse model enabled the examination of the effect of CCL2 on macrophage infiltration, collagen remodelling, cyclic mammary gland regression and DMBA-induced cancer risk." (PMID 28077158, 2017). "In cancer cells, CCL2 has been identified as a mediator of FXYD5 effects on cell migration." (PMID 28620381, 2017). "In addition, pharmacological inhibition of PPARγ with antagonist T0070907 significantly increased the expression of key cancer immunity-enhancing inflammatory factors including CCL2 and IL8 in the PPARG-amplified 5637 cells." (PMID 28740126, 2017). "In addition to the novel cancer genome-phenotype association, we further show here that mutant KRAS-driven MPE is mediated via CCL2-dependent paracrine signalling to CD11b+Gr1+ myeloid cells." (PMID 28508873, 2017). "Although CCL2 has been detected in human and mouse mammary epithelium, its role in regulating mammary gland development and cancer risk has not been explored." (PMID 28077158, 2017). "Indeed, we have shown that S1P released from apoptotic cancer cells, acted as a “come and get me” signal and attracted monocytes to almost the same extent as monocyte chemoattractant protein-1 (MCP-1/CCL2)." (PMID 27800303, 2016). "CCL2 plays a critical role in tumorigenesis in other types of cancer, but its role in ccRCC remains unclear." (PMID 27666332, 2016). "Another study suggested that CCL2/CCR2 axis could promote cancer metastasis by up-regulation of MMP2/9 through ERK1/2 signaling pathway." (PMID 27409666, 2016). "The production of IL-8 and CCL2 has been demonstrated for several cancer cell types." (PMID 26625205, 2016). "Of these, CCL2 together with its cognate receptor CCR2 have been shown to play key roles in cancer metastasis by sustaining cancer cell proliferation and survival, stimulating cancer cell migration and invasion, and inducing deleterious inflammation and angiogenesis." (PMID 26885690, 2016). "Cancer cells often secrete MΦ2-type cytokines such as IL-10, CCL2, CXCL12, and VEGF." (PMID 27231721, 2016). "Blocking CCL2/CCR2 signaling pathway may serve as a novel strategy to help patients with certain kinds of cancers." (PMID 27409666, 2016). "Previous studies revealed that CCL2 could regulate angiogenesis process in cancer development and metastasis through its critical role in macrophage recruitment." (PMID 27145753, 2016). "Among several chemokines, CCL1, −2, −4, −5, −7, −8, −12, −13, and IL6 might influence the interaction of inflammation with cancer malignancy, and CCL2, −3, −5, −7, CXCL12, −14, and IL6 were found to be able to affect the macrophage infiltration." (PMID 26790618, 2016). "Because CCL2 is a potent chemoattractant for TAMs, it may indirectly promote the intravasation and extravasation process of cancer cells." (PMID 26885690, 2016). "Finally, we reported that curcumin, a powerful natural drug, suppressed the production of EGF and CCL2 in macrophages and cancer cells, respectively, blocking the feedback loop and suppressing the migration and invasion of HNSCC cells." (PMID 27888616, 2016).
cancer (continued). "Previously, very limited evidence suggested that CCL2 may stimulate NF-κB signaling in cancer cells." (PMID 26317041, 2015). "In murine models, inhibition of CCL2 decreased the weight of the cancer nodes." (PMID 25695619, 2015). "However the role of CCL2 produced by the cancer cells appears to be confined to altering the macrophage phenotype, as cancer cells themselves were unaffected by inhibition of CCR2." (PMID 26174804, 2015). "It is acknowledged that cancer patients often have augmented production of immature cells; therefore some indication as to the functionality of monocytes and their ability to differentiate in the context of CCL2 neutralisation would be useful." (PMID 25990313, 2015). "Increased cancer cell migration was suppressed by the inhibition of CCL2 and CXCL8." (PMID 26284488, 2015). "CCL2 is produced by stromal cells, osteoblasts, endothelial and cancer cells in the microenvironment and can stimulate monocyte recruitment, osteoclast maturation and cancer cell growth and survival." (PMID 26317041, 2015). "CCL2 is overexpressed in various cancer types such as lung, breast and prostate cancer." (PMID 26294325, 2015). "The pleiotropic roles of CCL2 in the development of cancer are mediated through its receptor, CCR2." (PMID 24106481, 2013). "Our results are in contrast to those observed by others using CCL2/CCR2 targeted cancer models." (PMID 23372702, 2013). "We have shown that TGF-β-induced-Snail not only induces metastasis-causing epithelial-to-mesenchymal transition (EMT) of cancer cells but also enhances production of immunosuppressive cytokines and chemokines, including TGF-β, IL-10, CCL2, and TSP-1, which further promotes metastasis." (PMID 23755373, 2013). "Furthermore, tissue samples from CCL2-positive PCa patients had more macrophage infiltration than those from CCL2-negative PCa patients, consistent with previous reports showing CCL2 promotes cancer progression via enhancement of macrophage recruitment." (PMID 23982944, 2013). "CCL2 is a major inflammatory chemokine that also participates in the regulation of cancer disease." (PMID 22279523, 2012). "Finally a soluble CCR2-Ig that selectively neutralizes CCL2 was then used to determine the direct contribution of the autocrine interaction of CCL2-CCR2 on the cancer cells to tumor growth." (PMID 22279523, 2012). "The study also reported that loss of heterozygosity (LOH) in the CCL2 gene was more frequent in advanced tumors than in earlier stages suggesting it was associated with progression and not initiation of the cancer." (PMID 22687175, 2012). "This further emphasizes the important role of CCL2 as a target for therapy of cancer diseases." (PMID 22279523, 2012). "For the purposes of the microarray data validation, we have selected 9 genes that may play the most important role in cancer cells-macrophages interactions: CCL2, CCL3, CD163, CSF1R, HIF1, Il-18, MMP9, VEGF-C, and Wnt7b." (PMID 22353646, 2012). "Interfering with the CCL2/CCR2 ligand/receptor pathway may be of meaningful use in cancer therapy and we here tested whether the CCR2-selective, pro-apoptotic effects of GMME1 we observed previously could be utilized in such a setting." (PMID 21943176, 2011). "Since CCL2 has been reported to be regulated by NF-κB in both normal and cancer cells, we further examined the effect of rVP1 on NF-κB activation and determined whether it is also mediated by Akt." (PMID 21826248, 2011). "Research interest in developing cancer therapeutics that target CCL2 is increasing rapidly." (PMID 21826248, 2011). "There have been meaningful attempts at targeting the CCL2/CCR2 pathway for cancer therapy." (PMID 21943176, 2011). "Consequently, CCL2 expression was significantly higher in the cocultured cancer cells." (PMID 41160815, 2026). "Additionally, we conducted indirect coculture experiments to confirm whether inhibiting the CCL2/CCR2/PPARα axis in ADSCs affects cancer cell proliferation." (PMID 41160815, 2026).
cancer (continued). "Notably, Schwann cells (SCs) in the CNS, specifically nerve repair subtypes, can enhance immune cell chemotaxis by the release of chemokines, e.g., SCs can promote the recruitment and immuno-inhibitory function of MDSCs and release C-C motif chemokine ligand 2 (CCL2) to aid in cancer progression." (PMID 40376000, 2025). "Furthermore, blocking the CCL2 in CM from compressed carcinoma cells by neutralizing antibody could abolish macrophages migration." (PMID 39737867, 2025). "Drugs that block the chemokine monocyte chemoattractant protein 1 (MCP-1 or CCL2) downstream of TWEAK can significantly reduce the growth of CCA xenografts, while TWEAK overexpression promotes the proliferation and collagen deposition of cancer-associated fibroblasts." (PMID 39290697, 2024). "While the similarity of the cytokines secreted by the MSCs and cancer cells is surprising, these increase in the secretion of two inflammatory cytokine, IL-6 and CCL2, suggests that even 120 h co-culturing with cancer cells could lead MSCs to establish a pro-inflammatory microenvironment." (PMID 38674102, 2024). "In addition, CCL2 could contribute to cancer development in anti-TIF1-γ antibody-positive DM patients." (PMID 36357631, 2023). "Hence, studies show that IL-6 may help sustain cancer stem cell populations and increase EMT, whereas IL-4, CCL-2 and exosomal miRNA from cancer cells cause M2 polarization of TAMs." (PMID 37173970, 2023). "Thus, Twist1 expression was sufficient to induce CCL2 in normal and cancer mammary epithelial cells, and the expression of Twist1 may account for the elevated CCL2 expression in BC cells with mesenchymal characteristics." (PMID 37208442, 2023). "Accordingly, the blockade of CCL2 may prevent the development of cancer metastases." (PMID 36451019, 2023). "In addition, the expression of CCL2 has been found to be independent on NF-κB in cancer cells." (PMID 37828986, 2023). "Hence, CCL2/CCR2 signaling axis inhibition or blocking has been of interest for cancer therapy." (PMID 37892995, 2023). "In addition, CCL2 and IL-16 produced by MSCs have been shown to influence the survival of cancer cells in many types of cancer, including hematological malignancies, and their plasma levels were found to be elevated in AML and other hematological malignancies patients." (PMID 37932837, 2023). "Gene set enrichment analysis (GSEA) of RNA-seq from TGCT specimens of the Cancer Genome Atlas database representing major biological processes revealed increased expression of the Extracellular Matrix Organization and the Activation of Matrix Metalloproteinases gene sets (High CCL2 vs low CCL2)." (PMID 37352031, 2023). "Furthermore, CCL2 plays a particularly important role in cancer progression." (PMID 36077785, 2022). "Therefore, further studies are required to assess these mechanisms and whether the β-catenin/CCL2 axis can be found in other types of cancers." (PMID 35562953, 2022). "However, whether Vav2-Rac1 may exert their pleiotropic effects on cancer cells treated with CCL2 as a complex remains unclear." (PMID 35177591, 2022). "In addition, the possible mechanisms by which CCL2 participates in anticancer drug resistance are discussed, which may provide new therapeutic targets for reversing cancer resistance." (PMID 36077785, 2022). "Notably, CCL2 is also frequently overexpressed in drug-resistant cancer cells." (PMID 36077785, 2022). "Moreover, CO-IP and confocal microscopy results revealed that the binding of Vav2 and Rac1 was enhanced in cancer cells following treatment with CCL2, which indicated that CCL2 induces the functional coupling of Vav2 and Rac1 and the formation of the Vav2-Rac1 molecular complex." (PMID 35177591, 2022).